IL6 (interleukin 6)
Diseases named in the same sentence as IL6 in open-access papers (continued):
Sharing a sentence is not in itself a finding about the gene and the disease.
psoriasis (continued). "Among them, the p38 MAPK signaling pathway is the most closely related to the development of progression of psoriasis, which can promote the secretion of inflammatory cytokines (e.g, IL-6, IL-1β, and TNF-α) to accelerate the progression of psoriasis." (PMID 36618400, 2022). "The mRNA levels of psoriasis‐related inflammatory factors such as TNF‐α, IL‐23, IL‐17A, IL‐1β and IL‐6 were measured by RT‐PCR." (PMID 35023281, 2022). "Promising findings of a recent study demonstrated that Yangxue Jiedu Soup significantly decreased the secretion of Hsp70-containing exosomes in the plasma of psoriasis model mice by downregulating the production of TNF-α, IL-6, IL-1β, IFN-γ, IL-17, and IL-23." (PMID 36233237, 2022). "Immunohistochemistry was performed to confirm the counts of Ki67+, CD3+, IL-6+, and TNF-α+ cells in psoriasis skin lesions." (PMID 35359454, 2022). "In patients with psoriasis, the antagonism of TNF-α with etanercept also reduced the circulating levels of inflammatory and cardiovascular proteins, such as TNF-α, IL-1β, IL-6, and IL-8." (PMID 34674004, 2022). "Because DXM has a potent antioxidant effect, it can reduce the expression of proinflammatory cytokines, such as IL-6 and TNF-α, and inhibit inflammatory changes in psoriasis." (PMID 35629363, 2022). "Our results showed that spleen weight and cytokine levels, including IL-17A, IL-22, IL-23, IL-6, and IFN-γ, increased in the IMQ-induced psoriasis-like dermatitis mice." (PMID 35682849, 2022). "IL-6 and IL-22 are Th17-related cytokines that activate STAT3 synergistically and contribute to the pathological development of psoriasis." (PMID 35351863, 2022). "Leptin promotes IL-1, IL-6 and TNF-α production through its proinflammatory activity, which also affects psoriasis." (PMID 35216228, 2022). "The abnormal production of inflammatory cytokines, such as TNF-α, IL-6, IL-17 and IL-23, are confirmed to play key roles in psoriasis.The protein level of IARS was up-regulated in NHEKs treated with TNF-α, IL-6, IL-17 and IL-23." (PMID 36419191, 2022). "Psoriasis and CAD are however known to share certain cytokines, including IFNγ, TNF, IL-6, and IL-1793,94." (PMID 36323703, 2022). "The transcription factor activated by all three MAPK pathways, AP-1, is also important in the regulation of transcription of many molecules, including cytokines involved in psoriasis pathogenesis such as TNF-α and IL-6." (PMID 35883760, 2022). "During this process, inflammatory cytokines: TNF‐α, IL‐1β, IL‐6, IL‐17a, and CXCL‐15 were infiltrated in skin and contributed to psoriasis." (PMID 35281792, 2022). "From the t-test between serum metabolites and cytokines from psoriasis patients and healthy volunteers, seven candidate signature molecules were obtained: DMG, Gly and Ile, together with IL-6, CCL4, IL1-ra, and IL-8." (PMID 34006909, 2021). "Therefore, IL-6 could be pro-inflammatory during late phase of psoriasis pathogenesis." (PMID 34215755, 2021). "JAK inhibitors suppress the JAK/STAT signaling pathways and, thus, block the effects of inflammatory cytokines, such as IL-6, IFN-γ, IL-22, and IL-21, which are involved in the pathogenesis of psoriasis." (PMID 34501328, 2021). "In serum, a significant increase of IL-1ra (p = 0.02), IL-6 (p = 0.01), as well as CCL4 (p = 0.03) was observed in psoriasis patients compared with healthy subjects." (PMID 34006909, 2021). "The result showed that five gene sets were significantly enriched in psoriasis samples, including inflammatory response, TNF-α signaling via NF-κB, IFN-α/β response and IL-6/JAK/STAT3 signaling." (PMID 33613635, 2021). "Psoriasis patients who were asymptomatic for SARS-COV-2 exhibited immune imbalance with high levels of IL-18, IL-17A and IL-6, and low levels of IL-27 compared to healthy controls." (PMID 34068473, 2021). "Levels of cytokines such as IL-6, TNF-α, angiogenic factors, and adhesion molecules are elevated in obesity psoriasis and ischaemic heart disease." (PMID 35010995, 2021).
psoriasis (continued). "The pro-inflammatory cytokines, such as IL-6, TNF-α, IL-1β, IL-22, and IL-17A, have been reported to be up-regulated in psoriatic lesioned tissue and serum, and these cytokines likely drive the psoriasis pathogenesis." (PMID 33323018, 2021). "Glycyrrhizin is a therapeutic substance that improves psoriasis by down-regulating IL-17A and INF-γ, and further inhibits the expression of IL-6, TNF-α, and CCL20 induced by IL-17A." (PMID 34044769, 2021). "The present study showed that alantolactone decreased the mRNA levels of TNF-α, IL-6, IL-1β, IL-8, IL-17A, and IL-23, thereby suppressing Th1- and Th17-mediated cytokines and improving IMQ-induced psoriasis-like skin lesions and inflammation status in mice." (PMID 34202301, 2021). "Th17 lymphocytes differentiate under the influence of IL-23, IL-1β, TGF-β and IL-6, secrete IL-17A, IL-17F, TNF-α, IL-21, IL-22, and IL-26, and they play a crucial role in the maintenance of psoriasis chronic inflammation." (PMID 34769005, 2021). "We then analyzed the cells for markers typical for psoriasis, e.g., the expression of DEFB4A (coding for β-defensin 2), as well as the increase of the pro-inflammatory cytokines IL-6 and IL-8." (PMID 33801280, 2021). "In psoriasis, activation of NF-κB and STAT3 in keratinocytes results in the production of pro-inflammatory cytokines such as IL-6 and IL-8." (PMID 34641358, 2021). "A study conducted by this research team showed that regular coffee consumption increased IL-6, CRP, and TNF-alpha levels, which translated into clinical severity of psoriasis symptoms." (PMID 35010995, 2021). "While in groups in which psoriasis was induced and treated with different formulations showed reduced levels of both TNF-α and IL–6." (PMID 34947782, 2021). "IL-6 and IL-22, which are potent STAT3 activators, are known for their synergistic action with IL-17A in the pathogenesis of psoriasis." (PMID 34445513, 2021). "PPPs altered the mRNA expressions of the inflammatory cytokines (TNF-α, IL-6, and IL-1β) and improved the expressions of AQP3 and FLG in psoriasis-like mouse skin." (PMID 35153762, 2021). "The increased production of pro-inflammatory mediators and chemokines such as IL-1, IL-6, IL-23, IL-17, and TNF-α plays a crucial role in the pathogenesis of psoriasis." (PMID 35153762, 2021). "IκBζ is an important regulator of several psoriasis-related genes, including IL-17A downstream genes such as DEFB4, S100A7, and IL-6." (PMID 34445513, 2021). "In contrast, 983EVs treatment only significantly decreased IL-6, IL-17F, IL-36γ, and IL-36R, while the cytokines IL-36α and IL-36β were overexpressed compared to the only IMQ-induced psoriasis skin." (PMID 34884834, 2021). "The infiltrated neutrophils produce IL-6, IL-17A, and TNF-α to stimulate keratinocytes, resulting in positive feedback to deteriorate psoriasis." (PMID 33754014, 2021). "PPPs also attenuated the expressions of CD3 and Ki67 in psoriasis-like mouse skin and suppressed the serum or skin levels of pro-inflammatory cytokines, such as tumor necrosis factor alpha (TNF-α), interleukin 6 (IL-6), IL-1β, IL-8, IL-17, and IL-23." (PMID 35153762, 2021). "NF-κB can bind to the promotor of several pro-inflammatory cytokines such as IL-1β, IL-6 and TNF-α that are involved in the pathogenesis of psoriasis." (PMID 33801280, 2021). "The function of regulation for a variety of inflammatory molecules such as TNFα, IL-6, MIP-1B, and iNOS has been reported, which also plays an important role in the pathogenesis of psoriasis." (PMID 34395618, 2021). "In psoriasis, lipopolysaccharide mediates nuclear transduction of NF-κB, then proinflammatory factors including TNF-α, IL6, and prostaglandin E (PGE) up- regulate in keratinocytes." (PMID 34122426, 2021). "Psoriasis patients with severe depressive symptoms were found higher levels of inflammatory cytokines in the peripheral blood such as TNF-α, IL-6, and IL-17 than those with low depressive patients." (PMID 35004741, 2021).
psoriasis (continued). "In moderate-to-severe psoriasis, increased levels of pro-inflammatory markers and cytokines, such as TNF-α, IL-6, IL-17, IL-23, PCR, and others, have been detected not only in skin plaques, but also in the blood and other biological fluids, such as saliva." (PMID 34829740, 2021). "Enriched pathways shared between psoriasis and PRP included defense response, phosphatidylinositol acyl-chain remodeling, keratinization, and IL-6 production." (PMID 34491907, 2021). "Many cytokines including interferon-gamma (INF-γ), IL-6, and TNF-α have been identified in the pathogenesis of OP, and these are the same as those involved in the inflammation of psoriasis." (PMID 32635380, 2020). "IL-1β, IL-6 and TNF-α are important proinflammatory cytokins, especially TNF-α, involving in psoriasis pathogenesis." (PMID 33081840, 2020). "BAIAP2 has been shown to control the expression of the proinflammatory cytokines IL-6 and IL-1α, and PRKCZ has been noted to play a role in controlling inflammatory dermal mesenchymal stem cells in psoriasis, a T cell-mediated disease." (PMID 32117236, 2020). "Patients affected by psoriasis showed high levels of pro-inflammatory cytokines such as TNF-α, IL-6, and IL12 that exacerbate the inflammatory response." (PMID 32708987, 2020). "The mechanism of its action in psoriasis pathogenesis is to prime keratinocytes and neutrophils for enhanced production of proinflammatory cytokines (TNF-α, IL-6, and IL-8)." (PMID 32377165, 2020). "During psoriasis development, the increased expression of inflammatory cytokines, such as tumor necrosis factor (TNF)-α, interleukin (IL)-6, IL-17A, and IL-22 triggers uncontrolled inflammatory states and activates keratinocyte hyperproliferation." (PMID 32515468, 2020). "Meanwhile, the expression of inflammatory factors (IL-1β, IL-6, TNF-α, IL-17, and IL-22) in serum and kidney tissue of psoriasis-like mice was significantly increased." (PMID 32090080, 2020). "The human and bacterial RNA complexed with LL-37 not only stimulate PMNs from psoriasis patients that respond via TLR8 by producing TNF-α, IL-6, IL-8, and IL-1β, and NET-release; they also can be released by PMNs." (PMID 32509872, 2020). "Among the several pro-inflammatory cytokines involved in psoriasis, TNF-α, IL-6, and IL-12 are usually increased in psoriatic patients, creating a negative loop that exacerbates the inflammatory condition." (PMID 32059361, 2020). "Leptin induces IL-6, CXCL-1, IL-8 and MCP-1 production, which is involved in the hyperproliferation of the epidermis in psoriasis." (PMID 32397568, 2020). "Collectively, PD-1 signal blockade-induced psoriasis-like dermatitis is mediated by PD-1 signaling on CD8 T cells, and furthermore, IL-6 is likely to be a therapeutic target for the dermatitis." (PMID 33060784, 2020). "In the present study, MHP1-AcN was shown to inhibit TLR7/8 agonist-induced IL-6 production in RAW 264.7 cells and in a mouse model of psoriasis at the early stage of disease." (PMID 31659208, 2019). "The experimental results of this study show that the EPS/CPT emulsion can effectively reduce the levels of the inflammatory factors IL6 and TNF in peripheral blood to alleviate the symptoms of psoriasis." (PMID 31861934, 2019). "The expression of specific pro‐inflammatory cytokines/alarmins, such as IL‐17A, IL‐6, and lipocalin‐2 (LCN2), was higher in the serum of DKO* mice compared to DKO*K15 mice at day 30 after psoriasis‐like induction." (PMID 31556482, 2019). "In patients with psoriasis, TGFβ-1 induces the generation of FOXP3 positive Treg cells in the absence of IL-6 and the production of Th-17 cells in the presence of IL-6." (PMID 30744173, 2019). "The expressions of crucial inflammatory mediators (including IL-1β, IL-2, IL-6, IL-10, IL-17, IL-22, IL-23, IFN-γ, TNF-α) in skin tissues were measured by ELISA due to the import role of inflammatory cytokines in psoriasis." (PMID 31181689, 2019).
psoriasis (continued). "Immunopositivity for the antibodies anti-IL6, anti-IL17, and anti-IL23 revealed cytoplasmic staining, mainly basal and parabasal, in both psoriasis and geographic tongue." (PMID 31789253, 2019). "Current results have revealed that IL-6 is increased under the psoriatic status and positively correlates with PASI scores, at least in the more severe form of psoriasis." (PMID 31521168, 2019). "Stimulated by activated macrophages in adipose tissue, adipocytes secrete adipokines such as IL-6, TNF-α, visfatin and leptin, which also play an important role in the pathogenesis of psoriasis." (PMID 29696068, 2018). "TWEAK/Fn14 signaling contributes to the development of psoriasis by upregulating the TNFR2, EGFR, and keratin 17 expressions in keratinocytes and the IL-6 expression in DMECs." (PMID 30038329, 2018). "Curcumin has been reported to be an anti-psoriasis drug candidate by interrupting certain cytokines including TNF-α, IL-17, IL6 and INF-γ." (PMID 30301277, 2018). "On the other hand, IL-6 promotes the production of T helper (Th) 17 cells and, together with TNF-α, plays a central role in the development of psoriasis lesions." (PMID 29619128, 2018). "Th17 cells are derived from CD4+T cells in the presence of IL-6, IL-23, and TGF-β, which play a central role inthe chronic inflammatory diseases (psoriasis in particular) and are consideredresponsible for the chronic course of psoriasis." (PMID 29630472, 2018). "This study aimed to explore the effects of IL-6 targeting by let-7b and ERK1/2 mediated signaling on keratinocyte differentiation in psoriasis." (PMID 30219085, 2018). "IL-23/IL-17/IL-22 axes produced by abnormal activation of Th17 cells play key roles in pathogenesis of psoriasis that stimulate keratinocyte proliferation and secretion of other inflammatory cytokines such as TNF-α, IL-1, IL-6, and IL-8." (PMID 29046044, 2017). "Cytokine and chemokine expression levels in the mouse skins were also determined because expressions of IL-6, IL-17, IL-22, CCL20 and CXCL1 were involved in the pathogenesis of psoriasis." (PMID 29138509, 2017). "Previous studies suggested that IL-6 signaling plays an important role in the development of IMQ-induced psoriasis-like skin disease and in spontaneous psoriasis." (PMID 26999594, 2016). "Recently, there has been an increasing interest in the Th 17 cell pathway and related pro-inflammatory cytokines in psoriasis, including interleukin (IL)-17 and IL23, which induce the production of inflammatory mediators such as IL1, IL6, IL8, and TNF-α." (PMID 26910469, 2016). "We, and others have shown that IL-6 and its downstream targets (e.g. Stat3) are involved in the pathogenicity of IMQ-induced psoriasis-like skin disease and development of psoriatic lesions." (PMID 26999594, 2016). "Moreover, there is also strong association between autoimmunity and psoriasis when analyzing new bone formations and bone erosion as cellular biomarkers such as osteoclast precursors; osteoprotegerin (OPG), matrix metalloproteinase 3, serum IL-6, and IL-2R alpha were found elevated." (PMID 26339139, 2015). "Some studies indicated that ghrelin has potent inhibitory effects on the mRNA and protein expression levels of proinflammatory cytokines, such as IL-6 and TNF-α, which are important in the pathogenesis of psoriasis." (PMID 25587268, 2014). "Increased levels of IL-6 have been observed in IBD, RA, systemic-onset juvenile chronic arthritis (JCA), osteoporosis, and psoriasis." (PMID 25674084, 2014). "Many immune-derived cytokines, including IL-23, IL-17A, IL-20, IL-22, IL-1β, IL-6, and TNF-a, are involved and interact as a network in the pathogenesis of psoriasis." (PMID 23825622, 2013). "We therefore evaluated the expression of selected cytokines and chemokines thought to contribute to initiation or maintenance of the inflammatory cascade in human psoriasis (e.g., TNF, IL22, IL6, CXCL1)." (PMID 21483750, 2011).
psoriasis (continued). "It regulates the transcription of many important mediators of inflammation and tissue destruction in the psoriasis including TNF, IL-1 and IL-6." (PMID 22125590, 2011). "We demonstrated that psoriasis-related transcripts, such as IFN-γ, TNF-α, IL-17A, CCL20, IL-23, IL-6, IL-1α and IL-22, were significantly enhanced in mouse ears treated with PL and rMCP-1 than those with 1×PBS control." (PMID 21311769, 2011). "In accordance, the expression of several cytokines assumed to play a role in the pathogenesis of psoriasis (i.e. IL-20, TNF, IL-8, and IL-6) are p38 MAPK-regulated." (PMID 20072629, 2010). "In psoriasis, the cytokine expression profile is selectively skewed toward a T1 (i.e., IL-2, TNF-α, IL-12, IFN-γ) and away from a T2 (i.e., IL-2, IL-5, IL-6, IL-10, IL-13) pattern." (PMID 20040934, 2008). "These examples highlight that biomarkers integrating multiple pathophysiological signals often behave nonlinearly, consistent with our observations for IL-6 in psoriasis." (PMID 41472738, 2025). "Psoriasis is characterized by the dermal and systemic secretion of certain pro-inflammatory cytokines of the Th1 and Th17 cytokine family, such as interferon-γ (IFN-γ), tumor necrosis factor (TNF), interleukin (IL)-6, IL-17, IL-22, and IL-23." (PMID 39775226, 2025). "Significantly elevated levels of IL-6 have been reported in active psoriatic plaques obtained from 35 patients with psoriasis, compared to biopsies from non-lesional skin." (PMID 40731810, 2025). "In psoriasis treatment, luteolin has shown strong anti-inflammatory properties in keratinocytes by inhibiting TNF-α-induced production of inflammatory mediators, including IL-6, IL-8, and VEGF." (PMID 40161116, 2025). "The bidirectional association between OSA and psoriasis suggests a common systemic inflammatory pathway The activity of IL-7, TNF, IL-6, and C-reactive protein was significantly increased in OSA patients, and the increase of this activity was also significantly correlated with psoriasis." (PMID 40166062, 2025). "Adipose tissue is a source of various proinflammatory cytokines, including adiponectin, leptin, resistin, TNF-α, and IL-6, participating in the pathogenesis of both psoriasis and non-alcoholic fatty liver disease (NFLD)." (PMID 41226807, 2025). "Proinflammatory cytokines, IL-6 and TNF-α, which are elevated in patients with psoriasis, are also involved in the stimulation of prothrombotic factors that may result in thrombosis." (PMID 40584532, 2025). "In this study, we found that the expression of miR-31 and Krt6 was significantly upregulated in IL-6-induced psoriasis-like keratinocytes; however, treatment with PSORI-CM01 significantly decreased the expression of both miR-31 and Krt6 in this psoriasis-like keratinocytes." (PMID 40756706, 2025). "Importantly, compared to free TFC, TFC-Exo exerted higher suppressive effects on the expression of TNF-α, IL-23, IL-6 and IL-15 and better therapeutic effects on IMQ-induced psoriasis in mice." (PMID 39861699, 2025). "In addition, in the psoriasis group induced by IMQ, the levels of IL-1β, IL-6, TNF-α, and IL-17A were higher in the cko group than those in the wt group, especially IL-1β and IL-6 (p < 0.05)." (PMID 40430037, 2025). "In addition, IL-36G upregulates the expression of CCN1 and S100A7A, leading to the production of excessive pro-inflammatory factors by the cells, including IL-1, IL-6, IL-8, IL-36, and TNF, which promotes psoriasis." (PMID 40735322, 2025). "Serum biomarkers such as IL-6 and CCL20, elevated in preclinical models, correlate with subclinical enthesitis and may predict articular progression in psoriasis patients." (PMID 41583484, 2025). "Similar to AD, psoriasis involves keratinocyte-driven activation of the NF-κB, JAK/STAT, and MAPK, which stimulate the production of pro-inflammatory cytokines such as IL-1β, IL-6, and TNF-α." (PMID 41479908, 2025).